MEF2C (myocyte enhancer factor 2C)
Diseases named in the same sentence as MEF2C in open-access papers (continued):
Sharing a sentence is not in itself a finding about the gene and the disease.
atherosclerosis (8 papers, 2015 to 2025). A disease characterized by the build-up of fatty material and calcium deposition in the arterial wall resulting in partial or complete occlusion of the arterial lumen. "MEF2C is a transcription factor in the Mef2 family involved in the development of atherosclerosis, and its deficiency upregulates atherosclerosis." (PMID 39758846, 2024). "MEF2C is known to protect against atherosclerosis by inhibiting TLR/NF-κB activation, SMC migration, and proliferation." (PMID 40362577, 2025). "MEF2C prevents atherosclerosis formation involving several mechanisms, including the inhibition of the TLR/NF-κB pathway." (PMID 37263799, 2023). "In this study we explored the interactions among MCM3AP-AS1, miR-448 and MEF2C in atherosclerosis." (PMID 37266599, 2023). "MCM3AP-AS1 is downregulated in atherosclerosis and may regulate the miR-448/MEF2C axis to suppress HAOSMCs proliferation." (PMID 37266599, 2023). "We found that MCM3AP-AS1 was downregulated in plasma of patients with atherosclerosis, and it may sponge miR-448 to upregulate MEF2C in HAOSMCs, thereby suppressing the proliferation of HAOSMCs." (PMID 37266599, 2023). "Subsequent functional annotation identified eight atherosclerosis-relevant candidate genes: transcription factors (KLF12, KLF6, KLF9, and MEF2C), epigenetic regulators (HDAC9), and signaling molecules (YAP1, SOCS6, and CDC25A)." (PMID 41373654, 2025). "Among IRF2 targets were the inhibitors of inflammation myocyte enhancer factor 2C (MEF2C) and annexin A1, (ANXA1, also known as lipocortin 1), which was recently shown to decrease atherosclerosis in a mouse model." (PMID 27068706, 2016).
developmental delay (8 papers, 2017 to 2025). "Only two of the 35 samples with rare DAGLA variants harbored a likely pathogenic variant in another gene known to be associated with seizures and developmental delay (GRIN2A in subject 061 and MEF2C in subject 044)." (PMID 29145497, 2017). "Additionally, MEF2C haploinsufficiency syndrome (MHS) results in severe developmental delay and intractable epilepsy, implying that MEF2C may be broadly involved in ASD and other neurodevelopmental disorders." (PMID 41125877, 2025).
osteoporosis (8 papers, 2011 to 2025). A condition of reduced bone mass, with decreased cortical thickness and a decrease in the number and size of the trabeculae of cancellous bone (but normal chemical composition), resulting in increased fracture incidence. "The MEF2C locus, which encodes the transcription factor MADS box transcription enhancer factor 2, polypeptide C (MEF2C), is strongly associated with adult osteoporosis and osteoporotic fractures." (PMID 33424022, 2021). "A genome-wide association study found that genes associated with sarcopenia and osteoporosis include growth differentiation factor 8, myocyte enhancer factor 2C, and peroxisome proliferator receptor gamma coactivator 1a." (PMID 31796090, 2019). "In conclusion, SNHG14 activated autophagy via regulating miR-493-5p/Mef2c axis to alleviate osteoporosis progression." (PMID 37925525, 2023). "SNHG14 regulates the expression of Mef2c and activates autophagy through miR-493-5p, promoting osteogenic differentiation of BMSCs and consequently alleviating osteoporosis development." (PMID 37925525, 2023). "It has demonstrated that SNHG14 by regulating miR-493-5p/Mef2c-mediated autophagy activation, leading to the promotion effect on osteogenic differentiation of BMSCs, thereby improving osteoporosis progression." (PMID 37925525, 2023). "However, the biological role of Mef2c in osteoporosis and related bone formation is multidirectional." (PMID 37925525, 2023). "In short, SNHG14 activated autophagy via regulating miR-493-5p/Mef2c axis to alleviate osteoporosis progression, which might provide a new molecular target for osteoporosis treatment." (PMID 37925525, 2023). "Moreover, miR-27a has been reported to increase osteogenesis and decrease adipogenesis via targeting of myocyte enhancer factor 2C (Mef2c), and miR-27a was downregulated in osteoporosis patients." (PMID 36346531, 2022). "Therefore, we hypothesized that SNHG14 regulated the expression of Mef2c and activated autophagy through miR-493-5p, promoting osteogenic differentiation of BMSCs, thus alleviating osteoporosis development." (PMID 37925525, 2023). "Comparison of our GWAS data with SNPs identified in previous GWASs on osteoporosis showed five SNPs in three genes (PLCL1, DOK6, and MEF2C) with P values below 0.05." (PMID 21573128, 2011). "The finally data showed that SNHG14 targeted miR-493-5p/Mef2c axis to regulate autophagy activation, resulting the promotion effect in osteogenic differentiation of BMSCs, suggesting SNHG14 might be an effective target for osteoporosis treatment." (PMID 37925525, 2023).
acute lymphoblastic leukemia (7 papers, 2013 to 2023). Leukemia with an acute onset, characterized by the presence of lymphoblasts in the bone marrow and the peripheral blood. "The ectopic overexpression of MEF2C (whose activity is known to be SIK controlled) in early thymocyte progenitor acute lymphoblastic leukemia promotes B-cell development and inhibits early T-cell differentiation." (PMID 36731029, 2023). "Rearrangements that drive ectopic MEF2C expression have recurrently been found in patients with human early thymocyte progenitor acute lymphoblastic leukemia (ETP-ALL)." (PMID 35536646, 2022). "Treatment of the LOUCY acute lymphoblastic leukemia cell line with HG-9-91-01 restored normal T-cell development, therefore suggesting that the SIKs impact lymphoid lineage decision-making via regulating MEF2C activity." (PMID 36731029, 2023). "High expression of MEF2C was found in lymphoblastic leukemia." (PMID 29137293, 2017).
osteosarcoma (7 papers, 2020 to 2025). A usually aggressive malignant bone-forming mesenchymal neoplasm, predominantly affecting adolescents and young adults. "Given that MEF2C was found to affect prognosis, immune infiltration and stemness in osteosarcoma patients in our previous study, we verified the expression of MEF2C in clinical tissues of osteosarcoma patients by immunohistochemical experiments." (PMID 36059448, 2022). "The results showed that MEF2C was significantly expressed in clinical tissues of osteosarcoma patients." (PMID 36059448, 2022). "We further confirmed the expression of MEF2C in osteosarcoma tissues by immunohistochemical experiments." (PMID 36059448, 2022). "Our subsequent study will further explore the effect of MEF2C on the stemness of osteosarcoma through experiments." (PMID 36059448, 2022). "It is interesting to observe that MEF2C, a significant gene affecting the development of B cells, leads to a poor prognosis of osteosarcoma." (PMID 36569871, 2022). "In this study, we initially verified the effect of MEF2C on the malignant phenotype of osteosarcoma by bioinformatics analysis, and verified the expression of MEF2C in osteosarcoma tissues by IHC." (PMID 36059448, 2022). "By conducting knockdown experiments in SAOS-2 cells, we here showed that MEF2C drives IBSP expression in line with reports in mouse MC3T3 cells and its pro-osteogenic role in this human osteosarcoma cell line." (PMID 32195247, 2020). "MEF2C and FOS can regulate the prognostic genes related to Osteosarcoma Metastasis." (PMID 36408691, 2023).
Anxiety (6 papers, 2014 to 2025). Intense feelings of nervousness, tension, or panic often arise in response to interpersonal stresses. "Open field test results showed normal behavior in locomotion and anxiety levels in lower motor neuron Mef2c-KD mice." (PMID 39920775, 2025). "To this end we tested Mef2C-KO and Mef2C-CTRL mice using a battery of behavioural tests for assessment of hippocampal-dependent spatial learning, working and long-term memory, social preference and anxiety." (PMID 28959042, 2017). "Targeted manipulation of MEF2C alleviates negative affect and anxiety-like behaviors while restoring dopaminergic neurotransmission, establishing MEF2C as a key molecular regulator linking long-term nerve injury to maladaptive reward circuitry and affective dysfunction." (PMID 41440060, 2025).
colon carcinoma (6 papers, 2011 to 2021). "Studies in T-ALL and colon cancer cells have indicated that MEF2C may inhibit BCL2-regulated apoptosis and can function as a regulator of cell proliferation." (PMID 26487643, 2015). "Also, it was indicated by the significantly down-regulated in colon cancer that MEF2C may play a role in CRC etiology." (PMID 22496748, 2012). "As shown in the interaction network, immune-related gene PLCG2 and IGF1, which are up-regulated in colon tumor samples, have significantly strong correlation with several TFs: FOXP3, IKZF1, CBX7, LMO2, MEF2C, EPAS1 and MAF." (PMID 33996273, 2021). "In the evaluated 20 colon cancer cell lines, all but one (UBE3A) gene promoters were hypermethylated with frequencies ranging from 20% (LEF1 and MEF2C) to 100% (CNRIP1)." (PMID 21777459, 2011).
diabetes (6 papers, 2008 to 2018). "Given the rapidly growing impact of diabetes and obesity, defining a role for MEF2C in skeletal muscle and whole body metabolism will be of great help to further understand metabolic disorders." (PMID 25789156, 2015). "Diabetes upregulated the expression of ANP, MEF2A, MEF2C and p300." (PMID 23497378, 2013). "However, other cardiac transcription factors including Nkx2.5, Mef2c and Tbx5 were not significantly altered by maternal diabetes or NAC treatment." (PMID 24533448, 2014).
meningioma (6 papers, 2021 to 2024). A generally slow growing tumor attached to the dura mater. "Recent studies have shown that MEF2C confers resistance to ferroptosis in meningioma by upregulating the transcription of NF2 and E‐Cadherin." (PMID 39350345, 2024). "The expression of these proteins is driven by the myocyte enhancer factor 2C, making it a promising factor to manipulate during meningioma treatment." (PMID 34926298, 2021). "Emerging evidence for the anti‐ferroptotic properties of MEF2C in meningioma and lung cancer suggests that it may activate ferroptosis suppressor genes through transcriptional regulation." (PMID 39350345, 2024). "Activation of MEF2C promotes the expression of NF2 and E-cadherin in meningiomas and causes ferroptosis in tumor cells.MEF2C may be a potential therapeutic target for ferroptosis in meningiomas." (PMID 36910646, 2023). "Therefore, MEF2C can be used as a potential molecular target for the treatment of aggressive meningiomas through modulating ferroptosis." (PMID 35530363, 2022). "Silencing MEF2C, the expression levels of NF2 and E-cadherin in meningiomas decreased, which inhibited the growth of meningiomas mediated by ferroptosis." (PMID 35530363, 2022).
asthma (5 papers, 2017 to 2025). "Within the bronchial epithelial cells of individuals with severe asthma, the expression of Mef2c is decreased compared to that in healthy controls." (PMID 37465640, 2023). "We postulated a novel microRNA-mRNA interaction in asthma that the upregulated mir-203a may target MEF2C, leading to the decreased cell proliferation in asthmatic bronchial epithelial cells." (PMID 29137293, 2017). "Interestingly, Mef2c is decreased in bronchial epithelial cells from mild and severe asthma patients compared to healthy controls, which could result from the elevated miR-223 levels in bronchial epithelial cells of asthma patients." (PMID 32509795, 2020). "The results showed that gene expressions of both MEF2C and MDGA1 were significantly downregulated in patients with either mild-moderate or severe asthma compared to normal controls." (PMID 29137293, 2017). "We proposed that aberrant regulations of mir-203a-MEF2C and mir-3065-3p-MDGA1, as well as downregulation of KCNJ2, play important roles in airway epithelial homeostasis in asthma." (PMID 29137293, 2017). "In conclusion, our study shows that aberrant regulations of mir-203a to MEF2C and mir-3065-3p to MDGA1, as well as downregulation of KCNJ2, play important roles in airway epithelial homeostasis in asthma." (PMID 29137293, 2017).
Cachexia (5 papers, 2012 to 2021). Severe weight loss, wasting of muscle, loss of appetite, and general debility related to a chronic disease. "Therefore it appeared that MEF2C is a promising target for intervention strategies to reverse or stabilize muscle loss in cachexia." (PMID 22361433, 2012). "Our prediction analyses also revealed microRNA miR-17 as an important regulator of transcripts, such as Cxcl12, Mef2c, Stat3, and Cav1, that are translated into proteins with a role in cancer cachexia." (PMID 31013615, 2019). "MEF2C is a myogenic transcription factor that plays a critical role in skeletal muscle development and differentiation, but is down-regulated in cachexia." (PMID 28035074, 2017). "The data presented in this study provide further insights into the molecular basis of muscle wasting due to cancer cachexia and highlight the potential role of MEF2C in the development of cachexia." (PMID 22361433, 2012). "MEF2C gene targets myozenin and myoglobin as well as myokinase were also altered during cachexia, suggesting dysregulated oxygen transport capacity and ATP regeneration in addition to distorted structural integrity." (PMID 22361433, 2012). "We observed that Mef2c mRNA levels decreased significantly after fasting and cachexia." (PMID 33806354, 2021).
congenital heart disease (5 papers, 2017 to 2021). A heart disease that is present at birth. "MEF2C is also associated with congenital human heart defects due to its regulatory function on teratocarcinoma-derived growth factor 1 expression (Tdgf1), which is essential for the early embryonic heart development." (PMID 29340119, 2017). "Myocyte enhancer factor-2C (Mef2C) is a core transcription factor during cardiac development, and the abnormal expression of Mef2C can cause abnormal cardiac development and lead to the occurrence of congenital heart disease." (PMID 32183703, 2020). "Recently, two studies have identified two individual MEF2C mutations in patients with SHF-related congenital heart disease (CHD), highlighting the importance of correct levels and function of MEF2C in human heart." (PMID 33245870, 2021). "MEF2C is the cardiac-specific markers and its expression is upregulated in congenital heart disease (CHD) due to downregulation of the expression of miR-29C." (PMID 29340119, 2017).
dementia (5 papers, 2014 to 2022). Loss of intellectual abilities interfering with an individual's social and occupational functions. "In this stratum, enrichment analysis of RRA cortex candidates showed an over-representation of genes involved in cardiac development and function (DLG1, JPH2 or MEF2C among others), supporting a cardiovascular etiology of dementia in this stratum." (PMID 33846280, 2021). "It will also be interesting to examine whether MEF2C studied in the context of other genes provides a stronger biomarker signal for dementia prediction than when examined in isolation." (PMID 34386032, 2021). "We observed association of general cognitive function with four genes previously associated with AD or neuropathological features of AD and related dementias (TOMM40, APOE, MEF2C and ABCG1)." (PMID 25644384, 2015).
dilated cardiomyopathy (5 papers, 2013 to 2022). Cardiomyopathy which is characterized by dilation and contractile dysfunction of the left and right ventricles. "For example, in a mouse model of myocyte enhance factor 2C (MEF2C) overexpression in the heart, which causes dilated cardiomyopathy, Gdf15 mRNA was significantly induced in the cardiomyopathic heart of adult mice." (PMID 30542297, 2018). "Loss-of-function (LoF) mutations in MEF2C have been implicated in dilated cardiomyopathy in humans." (PMID 34996843, 2022). "Similar to CRT-TG, mice with up-regulation of the MEF2c transcription factor in adult heart also show dilated cardiomyopathy." (PMID 23437120, 2013). "Accordingly, the authors demonstrated that transgenic mice previously published and exhibiting dilated cardiomyopathy secondary to overexpression of Mef2c, expressed, in fact, the γ fragment, whereas mice overexpressing MEF2c(γ-) appeared phenotypically normal." (PMID 34208388, 2021). "Recently, MEF2C mutations were founded in patients with heart disorders, including patent ductus arteriousus (PDA), double outlet right ventricle (DORV), ventricular septal defect (VSD) and dilated cardiomyopathy (DCM), accompanied with or without neurological symptoms." (PMID 30376817, 2018).
gastric cancer (5 papers, 2022 to 2024). A primary or metastatic malignant neoplasm involving the stomach. "MEF2C has been associated with DNA methylation and enhanced PD-L1 expression in gastric cancer." (PMID 36661663, 2022). "A study constructed a decision tree using mutations in PIK3CA, MEF2C, SLC11A1, and KIF15 to divided patient sub-cohorts with elevated PD-L1 expression, which contribute to identify the novel prognostic biomarkers of Gastric Cancer." (PMID 35359374, 2022). "Indeed, in gastric cancer cells, the opposite effects were observed with the knockdown of MEF2C, which led to enhanced migration." (PMID 37762600, 2023). "MEF2C and TRIM15 have previously been reported to be associated with gastric cancer." (PMID 36661663, 2022). "The same authors reported that certain genes might be used as prognostic factors in H. pylori-positive gastric cancer patients (CACNB2, PREX1, MEF2C, GNB4, GRIN2A), while others (CACNB2 and MEF2C) predict the overall survival in these patients." (PMID 38255710, 2024).
lymphoma (5 papers, 2015 to 2023). A malignant (clonal) proliferation of B- lymphocytes or T- lymphocytes which involves the lymph nodes, bone marrow and/or extranodal sites. "Additionally, gene expression profiling of Tcf7−/− lymphomas showed upregulated expression of myocyte enhancer factor 2c (Mef2c), which has been recently associated with an immature T-ALL subgroup." (PMID 28872614, 2017). "Finally, co-IP after cross-linking using a human lymphoma B cell line (BJAB) and an Abelson Murine Leukemia Virus (AMuLV)-transformed B cell line (pre-B) further show that MEF2C and EBF1 may exist in the same complex." (PMID 26900922, 2016).
myeloid leukaemia (5 papers, 2016 to 2023). "Mef2c is abnormally induced in leukaemic GMPs in myeloid leukaemia and knockdown of Mef2c attenuated the proliferative potential of these cells." (PMID 27507714, 2016). "Various animal models also show that MEF2C is important in myeloid leukaemia." (PMID 35092700, 2022). "In fact, MEF2C was proposed to promote metastases development in pancreatic adenocarcinoma by inducing metalloproteinase (MMP) 10 transcription and to promote myeloid leukaemia, behaving as an oncogene by cooperating with the Sox4 gene." (PMID 33673112, 2021). "Myeloid leukemias initiated through MLL-AF9 displayed increased Mef2c expression and required elevated MEF2C levels to maintain a high capacity for colony formation." (PMID 26506234, 2016).